RAG1 (recombination activating 1)
Diseases named in the same sentence as RAG1 in open-access papers (continued):
Sharing a sentence is not in itself a finding about the gene and the disease.
tumor (continued). "Additionally, the tumor suppressive efficacy of Usp22 inhibition was modest when MC38 tumor cells were implanted into RAG1-KO mice." (PMID 41252204, 2025). "Yet, it did match the frequency of EGFPOVA+ tumor cells from BPO/Rag1–/– mice." (PMID 41279375, 2025). "Subsequently, using CRISPR/Cas9 gene editing to individually knockout Xkr8 or TMEM16F, we show that both PS scramblases directly contribute to immune regulation and tumor growth in immune-competent mice but not in NOD/SCID or Rag1 KO immune-deficient mice." (PMID 41198619, 2025). "Accordingly, we developed tumor metastasis in Rag1–/– and NOD/SCID mice." (PMID 39545417, 2024). "The tumor growth was found to be increased in RAG1−/− as compared to WT mice, which could be due to the absence of adaptive immune response, especially the antitumor T-cell response." (PMID 39247196, 2024). "In addition, mouse xenograft tumor tissues from Postn-/-Rag1-/- mice displayed lower cell proliferation compared to tumors from Postn+/+Rag1-/- mice." (PMID 38773979, 2024). "Therefore, we assessed the effects of these compounds in immunodeficient subcutaneous KPARG12C tumour-bearing Rag1−/− mice which lack functional T and B lymphocytes and are incapable of inducing adaptive immune responses." (PMID 39322643, 2024). "Importantly, r3LCMV improved tumor control in immunodeficient Rag1–/– mice and MyD88–/– mice, suggesting that multiple pathways contributed to the antitumoral effects." (PMID 38861331, 2024). "Interestingly, on a Rag1-/- immunodeficient background, Alb-IKKβ(EE) mice showed a drastically reduced tumor burden, illustrating the pro-tumorigenic effect of the adaptive immune system." (PMID 38111571, 2023). "Furthermore, we have developed a RAG1 knockout FcRn+/+/HSA+/+ strain that we have used to investigate T-cell engager efficacy that should be applied to AlproTox anti-PC tumour investigations." (PMID 36243890, 2022). "Similarly, several genes responsible for T-cell differentiation such as rag1 and id3 were downregulated in DN stage of tumor samples." (PMID 35504924, 2022). "The suppressive effects of exogenous GSDMD expression on tumor progression were not noticed when B16 cells were implanted in immune-deficient Rag1−/− mice, highlighting the requirement of an intact immune system for tumor suppression by GSDMD." (PMID 36323669, 2022). "Arginase inhibition in cSCC tumors using Nω-hydroxy-nor-arginine (nor-NOHA) reduced tumor growth in B6 mice but not immunodeficient Rag1-deficient mice." (PMID 34031449, 2021). "In our murine tumor model, topical IMQ failed to inhibit the tumor growth in Rag1-deficient mice, suggesting that the IMQ-induced antitumor effect is dependent on adaptive immunity." (PMID 34439104, 2021). "However, we also observed that tumours grew even faster in Rag2−/−γc−/− mice compared to Rag1−/− mice." (PMID 33535624, 2021). "SVs in ETV6-RUNX1 positive tumours bear the hallmarks for RAG1 and RAG2 activity." (PMID 34753926, 2021). "Furthermore, by constructing MC38 tumor model using Rag1−/− mice (which lack T cells and B cells), we showed that anti-PVRIG mAb was effective even in the absence of adaptive immunity, suggesting the importance of NK cells in PVRIG-targeted treatments." (PMID 34174928, 2021). "Finally, ETV6-RUNX1 positive tumours were associated with enrichment for TBLXR1 and RAG1/RAG2 deletions." (PMID 34753926, 2021). "The results showed that topical IMQ failed to inhibit the tumor growth in Rag1-deficient mice, indicating that the antitumor effect of IMQ is dependent on adaptive immunity." (PMID 34439104, 2021). "To confirm this hypothesis, we transferred lymph node cell suspensions from tumor-bearing C57Black/5 mice donors to tumor-bearing RAG1-/- recipient mice." (PMID 33330068, 2020).
tumor (continued). "In these mice, spleen tissues revealed an increased expression of the Recombination Activating Gene 1/2 (RAG1/2) endonuclease that might be responsible for the high rate of abnormal IGH rearrangements observed in these neoplasias." (PMID 32503270, 2020). "We found that the TILs (Tumor Infiltrating Lymphocytes) from tumors growing in RAG1-/- mice transplanted with activated B cells and T cells from tumor bearing donors had a significantly higher conventional/regulatory T cell ratio than tumors from the other experimental groups." (PMID 29975708, 2018). "In addition, mDKN-01 anti-tumor activity is retained in a RAG1-/- mouse, highlighting the T cell independence and NK dependence of the anti-tumor mechanism." (PMID 30400822, 2018). "To further assess whether SENP3 is involved the regulation of Treg cell-mediated tumor immunosuppression by ROS, we carried out a side-by-side comparison using tumor-bearing Senp3+/+Foxp3-Cre, Senp3fl/flFoxp3-Cre, and Rag1−/− mice treated with NAC." (PMID 30089837, 2018). "After intravenous application into tumor-bearing Rag1-/- mice, we could confirm the very strong liver tropism of HAdV5HVR7 virus." (PMID 29386504, 2018). "Moreover, studying the mechanism of antitumoural action of LCMV-WE, we found that T cells were largely dispensable in our MOPC tumour model in Tcrab−/−, Rag1−/− and NOD/SCID mice." (PMID 28248314, 2017). "Tumor colonization was comparable between Rag1−/− and wild-type mice." (PMID 26981777, 2016). "However, all 14 Rag1−/− mice injected with clones 8 and 16 exhibited tumor growth and succumbed to tumor burden within 5 weeks postinjection." (PMID 27143385, 2016). "Interestingly, tumor growth was moderately slowed by Cxcl14 reexpression in Rag1−/− mice up to 14 days postinjection." (PMID 27143385, 2016). "Although CD40 signalling is critical for the differentiation of inflammatory monocytes into E-cadherin + inflammatory DCs and the promotion of anti-CD40-mediated colitis has been confirmed in Rag1 KO mice, little is known regarding the role of E-cadherin + inflammatory DCs in tumour immunity." (PMID 25651850, 2015). "Tumor growth was monitored by endoscopy weekly and developed faster in RAG1-/- mice." (PMID 25853550, 2015). "To determine whether the CD34− and CD34+ sphere-forming cells could initiate tumors in vivo, we inoculated Rag1 mice with 100 spheres from either CD34− or CD34+ tumor cells via the retro-orbital sinus, delivering them directly to the lungs." (PMID 25294815, 2014). "In vivo experiments in RAG1-/- mice showed that subcutaneous B16-F10 tumors treated with vMyx-IL15Rα-tdTr exhibited attenuated tumor growth and a significant survival benefit for the treated group compared to the PBS control and the control viruses (vMyx-IL15-tdTr and vMyx-tdTr)." (PMID 25329832, 2014). "In contrast, all 6 young Rag1-deficient C57BL/6 mice given no purified splenic T cells from wild-type C57BL/6 mice had progressive tumor cell growth." (PMID 23419047, 2013). "To determine whether the residual Treg population seen in PC61-treated mice might be sufficient to affect DC function in tumor-bearing mice, we examined tumor-specific T cell proliferation in RAG1−/− mice, which lack all T cells including Treg." (PMID 21390236, 2011). "Furthermore, in both RAG1−/− and immunologically intact mice, IL-18 correlated with greater tumor infiltration of macrophages and neutrophils." (PMID 21935389, 2011). "Notably, exogenous rIL-9 inhibited tumor growth in Rag1(−/−) mice but not in mast-cell-deficient mice, indicating that IL-9 targets in this context include mast cells but not T or B cells." (PMID 41148223, 2025).
tumor (continued). "Interestingly, Rag1–/– mice also exhibited a significant improvement in tumor control after r3LCMV treatment, demonstrating that r3LCMV could also induce antitumoral effects in the absence of adaptive immunity." (PMID 38861331, 2024). "We next applied clodronate encapsulated liposomes (CELs) treatment to deplete macrophages in tumor-bearing WT Rag1−/− mice and Rag1−/−NcDase−/− mice to examine whether macrophages are responsible for the differential tumor growth rates after CD8+ T cells transfer." (PMID 38302493, 2024). "Indeed, the immunoblots confirmed the upregulation of FOXO1 and RAG1 in FARSAKD Jeko cells, and overexpression of FARSA in Jeko and REC1 cells reversed their expression levels, thus supporting another activated tumor-promoting FOXO1-RAG1 signaling in the FARSA-manipulated MCL cells." (PMID 36675119, 2023). "Importantly, r3LCMV also improved tumor control in immunodeficient Rag1-/- mice." (PMID 38106001, 2023). "Using Rag1 deficient mice, we found that the adaptive immune system does not play a significant role in Myc/p53DD tumor engraftment or growth, nor in treatment-mediated tumor control." (PMID 35309309, 2022). "However, tumor growth was accelerated in CXCR5 or Rag1-KO mice." (PMID 35552285, 2022). "By contrast, in Rag1 (encoding recombination activating 1) knockout mice (which lack mature B and T cells), gut microbiome depletion could not prevent tumor development." (PMID 36510609, 2022). "Consistent with our results in Rag1−/− mice, we observed significantly slower tumor growth (P < 0.05) in humanized tumor-bearing mice treated with anti-hPVRIG mAb compared to those treated with control antibody, indicating that PVRIG blockade in humanized mice could benefit directly via NK cells." (PMID 34174928, 2021). "Furthermore, in a novel AlbuMus RAG1 knockout model (AlbuMus RAG1 KO) bearing EGFR-positive BRAF mutated tumours, we demonstrate superior anti-tumour effects after a single dose of the Albu-LiTE construct compared to a conventional Fc-less LiTE format and a full-length anti-EGFR monoclonal antibody." (PMID 33686177, 2021). "Therefore, TACE-treated HCC patients with low RAG1 expression may show low antitumor immune responses, rapid tumor progression, and thus, short OS time." (PMID 34646823, 2021). "The tumor numbers in the Lgr5/Arf1/Apc/IFNγ-KO and Lgr5/Arf1/Apc/Rag1-KO also significantly increased in comparison with those in the Lgr5/Arf1/Apc mice (Lgr5/Apc: 99.6 ± 8.9; Lgr5/Arf1/Apc: 41.0 ± 5.6; Lgr5/Arf1/Apc/Rag1-KO: 90.4 ± 11.0; Lgr5/Arf1/Apc/IFNγ-KO: 73.0 ± 9.5)." (PMID 31924786, 2020). "Therefore, to determine the relative and hierarchical involvement of different lymphocyte subsets in tumor control, we compared the growth of Ptgs−/− tumors in Rag1−/− mice or in wild-type mice depleted of either NK cells, CD4+ T cells, CD8+ T cells, or both CD4+ and CD8+ T cells." (PMID 33220234, 2020). "Indeed, transfer of Blimp-1-deficient CD4+ T cells into tumor-bearing-Rag-1-deficient mice did not control MCA205 tumor growth to the same extent as transfer of WT CD4+ T cells." (PMID 31924474, 2020). "Analysis of tumor lysates from control(M1, M2) and arsenic sulfide-treated(M3, M4) mice showed an obvious decrease in the expression of NFATc3 proteins, and there was a significant increase in RAG1 and γ-H2AX protein levels in the tumors from mice treated with arsenic sulfide." (PMID 31822296, 2019). "Therefore, we proceeded to in vivo experiments, where we activated isolated B lymphocytes with agonist anti-CD40 antibody, washed the cells thoroughly, mixed them with isolated T cells and immediately transferred all cells to RAG1-/- mice, previously injected with TC-1 tumor cells." (PMID 29975708, 2018).
tumor (continued). "Immunophenotyping of tumor specimens and experiments in Rag1-KO and CD8-KO demonstrated that smoke-induced tumor growth requires functional adaptive immunity." (PMID 40104059, 2025). "To eliminate the effects of tumor antigen spreading on bystander T cells and secondary sources of IFN-g production, we utilized Rag1−/− mice, which lack endogenous T and B cells." (PMID 40235478, 2025). "Next, to evaluate the anti-tumor activity of CBD in vivo, both immunocompetent and immunocompromised syngeneic mice models (wild-type C57BL/6J mice, athymic nude mice, and Rag1 KO mice) were used." (PMID 40475776, 2025). "To test the role of the adaptative immune system in this tumor control, we injected Luc-SIY+ tumors into Rag1 knockout (KO) mice and C57BL/6 mice." (PMID 38927950, 2024). "The similarity in response to combined inhibitor treatment in RAG-1-/- and RAG-2-/- γc-/- mice suggests that NK cells contribute little to the anti-tumour activity of the treatment." (PMID 37582853, 2023). "Using RAG1 knockout mice and CD8 T cell-depleting antibodies, we establish a role for adaptive immunity in mediating sustained irradiated tumor control with MMAE." (PMID 35790753, 2022). "Next, Rag1–/‐ and Rag1–/‐ Pdia4–/‐ mice bearing GK1 tumours were used to investigate the function of Pdia4 in T cell‐ and B cell‐implicated tumour development because T and B cells are deficient due to Rag1 ablation." (PMID 35170261, 2022). "Furthermore, greater growth inhibition of EGFR-positive BRAF mutated tumours was measured following a single dose of Albu-LiTE-HB construct compared to the Fc-less LiTE format and a full-length anti-EGFR monoclonal antibody in a new AlbuMus RAG1 knockout model introduced in this work." (PMID 33686177, 2021). "To further asses the importance of NK cells in PVRIG blockade, we used Rag1−/− mice (which lack both T cells and B cells) to construct the MC38 subcutaneous tumor model." (PMID 34174928, 2021). "To assess the impact of tumor-specific T cells on the growth of KPN1.1 tumors, we transplanted KPN1.1 tumors into C57BL/6J, Rag1−/−, “4get” GFP-tolerant mice, or NINJA(F) mice, which express NINJA in all tissues and are tolerant to GFP and the neoantigens)." (PMID 34632444, 2021). "By contrast, when mice were treated with donor IL-2 NK cells isolated from RAG-1 KO mice that lack the expression of the KIR2DL3 inhibitory receptor, half of them were still alive 70 days after tumor injection." (PMID 34071607, 2021). "Untreated tumours grew rapidly in both Rag1−/− and C57BL/6 mice, however, CHK1i+LDHU treated C57BL/6 controlled tumour growth more effectively than Rag1−/− mice, indicating a role for the adaptive immune system." (PMID 34359633, 2021). "Interestingly, in RAG1 KO mice bearing B16 tumors, the tumor growth inhibition effect of the indicated treatment (monotherapy or combined therapy) was obviously weaker than that of the same treatment in the presence of transferred CTLs in RAG1 KO mice bearing B16-OVA tumors." (PMID 31511064, 2019). "Similar to tumors receding in C57BL/6: Rag1-/- mice, tumor regression in C57BL/6: Rag1-/-; Il2rg-/- mice also was typified by a significant culling of GFP-positive tumor cells and a concomitant increase in fibrosis." (PMID 30936429, 2019). "Analyses of wild-type and immunodeficient RAG1 knockout mice transplanted with MC38 cells reveal that upregulation of checkpoint molecules and infiltration by Tregs are the major tumor escape mechanisms." (PMID 29296022, 2018).
tumor (continued). "The 5PT/HFFF2 interaction in vivo, within a xenograft tumor model grown in partially immune-compromised (RAG1−/−) mice, also generates an α-SMA-positive myofibroblastic stroma and promotes tumor growth (available online)." (PMID 28922779, 2018). "To determine if this cell population was activated by the infection, we reconstituted Rag1−/− mice with CD8+ T cells isolated from mice that had cleared CT26 tumors through infection and assessed CT26 tumor development." (PMID 26981777, 2016). "Importantly, Ptgs1/Ptgs2−/− tumors were able to grow in Rag1−/−, Tap1−/−, and Batf3−/− hosts, indicating that prostanoid deficiency did not impair tumor formation in a cell-intrinsic fashion but rather acted to prevent CD8α+/CD103+ DC-dependent rejection mediated by CD8+ T lymphocytes." (PMID 26343581, 2015). "Similar to the effect observed in RAG1-/- mice, C57BL/6 mice treated with vMyx-IL15Rα-tdTr also had significant intra-tumor infiltration of NK cells, compared to both tdTomato expressing virus and PBS treatment." (PMID 25329832, 2014). "To understand if CD200-mediated inhibition of tumor formation and metastasis observed in C57BL/6 mice were due to stimulation of adaptive immunity, we did similar experiments in Rag1−/− C57BL/6 mice." (PMID 22319630, 2012). "Our results provide evidence that both Xkr8 and TMEM16F knockout tumor cells suppress in vivo tumor growth in immunocompetent mice but not in NOD/SCID or Rag1 KO immuno-incompetent mice." (PMID 41198619, 2025). "To visualize the dynamic biodistribution and long-term performance of vaccine-boosted transferred T cells during the anti-tumor process, we used B16-OVA bearing Rag1−/− mice injected with OT-1 cells co-expressing luciferase, followed by immunization with the intranasal circRNA vaccine." (PMID 40122855, 2025). "Consistently, knockdown of Rfwd3 did not affect tumor growth or Ki67+ cell proportion in Rag1 KO mice." (PMID 41117130, 2025). "We found that CSE did not promote tumor growth in Rag1-KO mice; additionally, in these mice, gut microbiome depletion failed to decrease the tumor burden." (PMID 40104059, 2025). "Similar observations were noted in the Rag1 KO mice, which do not have matured T and B cells, whereby the Xkr8 KO tumors grew similarly as WT evident by both tumor volume and tumor weight." (PMID 40391322, 2025). "Immaturity of tumor cells was indicated by blast morphology and expression of rag1, which is not expressed in mature, quiescent B cells." (PMID 38117861, 2023). "B16F10-transplanted Rag1−/− mice exhibited no alterations in tumor growth between the PBS- and methionine-treated groups, indicating that the antitumor effect of methionine was mediated by T cells." (PMID 37147330, 2023). "In contrast, MC1R depletion did not affect tumor growth in immunodeficient TCRβ or RAG1 knockout mice." (PMID 37714844, 2023). "To address this issue and assess whether the increased CD8+ Tcell recruitment in KPA tumours promoted immune control, we crossed KPA miceonto a Rag1-/- background (KPAR) and evaluatedtumour growth in KPA and KPAR animals." (PMID 35930804, 2022). "This approach proved to be highly efficient for eradicating established Caski tumor xenografts in Rag1 mice, with 4 out of 5 mice showing no tumors present at day 77 evaluation point." (PMID 36139356, 2022). "Additionally, in our cell line model, where Rag1 KO mice were treated with WT or MK2 KO BMMs, we observed markedly suppressed tumor growth in mice treated with MK2 KO BMMs compared to animals treated with WT BMMs." (PMID 36362348, 2022). "Paradoxically, Arid1a ablation exhibited the inhibitory effects when tumor cells were engrafted in Rag1 null mice, suggesting that possible tumor or innate immune cell mediated mechanisms account for a negative role of ARID1A loss on tumor growth." (PMID 36435834, 2022). "Accordingly, the activation of Stat3 and expression of Vegfa, Vegfb, and Vegfc in GK1 tumours between Rag1–/‐ and Rag1–/‐ Pdia4–/– mice were not altered." (PMID 35170261, 2022).